CCL2 (C-C motif chemokine ligand 2)
Diseases named in the same sentence as CCL2 in open-access papers (continued):
Sharing a sentence is not in itself a finding about the gene and the disease.
tumor (continued). "Immunosuppressive cells, including M2-TAMs, myeloid cells, and MDSCs, secrete a variety of cytokines (IL-6, IL-10, IL-4Ra, FasL, CCL2, PGE2, EGF, VEGF, and MMP9) to suppress the function of cytotoxic T lymphocytes (CTLs) and promote the progression of tumour cells." (PMID 30777100, 2019). "Moreover, a previous study has found that targeting CCL2/CCR2 signaling with a CCR2 antagonist significantly reduces the recruitment and polarization of TAMs and thus enhances tumor immunotherapeutic effect." (PMID 30894684, 2019). "Additional RNAscope assays for IL6, CCL2, and POSTN were used to establish whether ANRIL correlated with increased tumor promoting cytokines." (PMID 31572679, 2019). "Some cytokines, chemokines or growth factors such as tumor growth factor-β (TGF-β), the chemokine C-C motif ligand 2 (CCL2), colony-stimulating factor 1 (CSF-1), C-X-C motif chemokine ligand 12 (CXCL12), or insulin-like growth factor 1 (IRF1) are induced by RT in the tumor environment." (PMID 31179236, 2019). "Moreover, the vascularity and tumor proliferation, as evaluated by CD34 (p = 0.0021) and KI-67 (p = 0.0451) staining, respectively, were higher in the CCL2-Vehicle group than in the Mock-Vehicle group." (PMID 31366997, 2019). "MSCs are also able to promote tumor growth and metastasize through direct cell-to-cell contact or through their secreted exosomes, which are able to carry different molecules such as IL-6, TFG-β1, CCL2, and fibronectin, or miR-375, miR340 and miR-155." (PMID 31547627, 2019). "The identification of SASP, including CCL2, may provide potential therapeutic targets in CRC as well as enhance our understanding of this important phenomenon in the context of tumor progression." (PMID 31545552, 2019). "In a preclinical model of HCC, blocking CCL2/CCR2 signaling with a CCR2 antagonist reduced Ly6Chi monocyte numbers in the peripheral blood and suppressed anti-inflammatory macrophage polarization in the liver, ultimately inhibiting tumor growth." (PMID 32047496, 2019). "Secondly, NLRP12 downregulates hepatocyte-specific expression of cytokines such as IL-6 and TNFα which promote proliferation and tumor growth, and chemokines CXCL1, CXCL2 and CCL2, which enhance inflammatory cell infiltration and thereby augment inflammation in the tumor milieu." (PMID 30990169, 2019). "Accumulating evidence indicates that monocytes (primarily iMo) are essential pre-metastatic promoters being rapidly recruited from the bone marrow to the pre-metastatic niche, mainly by CCL2/CCR2 axis, where they promote tumor colonization by secreting angiogenic factors, like VEGFA." (PMID 31447834, 2019). "CCL2 is certainly not the only culprit, but it is definitely present in the tumor microenvironment and has the potential to impact not only on cancer or stromal cells but also on myeloid cells." (PMID 31921102, 2019). "However, we found increased levels of CCL2, VEGF, and TGF-β1 also positively correlating with F4/80+ macrophages, high vascularization and collagen deposition during tumor progression in the 4T1 mouse model." (PMID 31334111, 2019). "CCL2, CCL11, CCL16, CCL18, and CXCL8 promote tumor angiogenesis and endothelial cell survival." (PMID 30894861, 2019). "Tumor-initiating cells with YAP hyperactivation recruit M2 macrophages at the early phases of cancer development, mainly through direct YAP–TEAD targeting of CCL2 and CSF1 (colony stimulating factor 1)." (PMID 31052239, 2019). "Additionally, it has been documented that hepatic macrophages release different mediators, including IL-6, IL-1β, CCL2, VEGF A (VEGFA), and TNF, to augment tumor cell proliferation in HCC." (PMID 32047496, 2019). "Our data proves tumor-promoting role of MAGEA3 and provides the rationale to target MAGEA3 and/or its functional mediators like CCL2 for PCA, which may have a better impact in PCA therapy." (PMID 31287009, 2019).
tumor (continued). "In details, the decrease of FGF2, FLT1, CCL2 mRNA, along with increase of SERPINF1 mRNA were observed in EP300 knockdown ESCC cells, predicting that EP300 may promote tumor initiation via angiogenesis in ESCC." (PMID 31632486, 2019). "Moreover, many of the factors de-repressed upon MITF knockdown are important players that activate anti-tumor immunity (e.g. IL15, CCL2), which suggests a potential role of MITF in evasion of immune surveillance." (PMID 31554806, 2019). "Breast and gastric tumor-derived exosomes can induce a M1 pro-inflammatory response in macrophages through the activation of NFκB, which in turn stimulates production of inflammatory cytokines including GCSF, IL-6, IL-8, IL-1β, CCL2, and TNF-α." (PMID 31555295, 2019). "Gene expression of IL- 6, IL-10, CCL2, c-Myc, iNOS, CSF-1R, and MMP9 was elevated in all three of the in vitro TAM preparations which suggests that in vitro generated TAM are immunosuppressive and thus tumor promoting." (PMID 31138333, 2019). "Based on these results, we hypothesized that the combination of CCL2 secretion of GBM and macrophage infiltration likely plays a critical role in promoting tumor angiogenesis, which encouraged us to perform in vivo studies." (PMID 31366997, 2019). "Further analysis showed that macrophage chemoattractants MCP-1 (CCL2) and MIP-1α (CCL3) and neutrophil chemoattractants MIP-2 (CXCL2) and KC (CXCL1) were significantly elevated, and these chemokines were secreted by K-ras activated tumor cells." (PMID 32039025, 2019). "In addition to recruiting myeloid cells, the group also found that tumor- and TAM-secreted CCL2 can lead to the recruitment of Tregs through CCR4, further dampening the ability of CTLs to exert anti-tumor effect." (PMID 31396227, 2019). "Low expression of Klotho, or high expression of CCL2 proteins in tumor tissues, could be correlated with poor overall survival of CRC patients, suggesting that CCL2 represents a promising relevant biomarker and potential target for CRC." (PMID 31545552, 2019). "In this study, we evaluated the expression of CCL2, IL18, TNF-α, and IL23α, and whether they play a role in tumor progression or suppression." (PMID 32695310, 2019). "In this report, intra-tumoral injection with STING ligand resulted in elevated levels of TNFα, IL6 and CCL2, but no significant increase in IFNγ within the Panc02 tumor microenvironment." (PMID 31036082, 2019). "Besides M-CSF, the CC chemokines CCL2, CCL3, CCL4, and CCL5 are well-recognized chemotactic factors for macrophage populations in the tumor." (PMID 30245686, 2018). "Other chemokines such as CCL2, CCL3, CCL4 promote tumour invasion and metastases." (PMID 29719625, 2018). "Another approach to target the CCL-2/CCR-2 axis is to use siRNA, which targets CCL-2 expression in vivo by a complex of siRNAs with tumor penetrating peptides by non-covalent calcium cross-linking." (PMID 28660349, 2018). "CCL2 and LCN2 from tumor cells induce EMT and generation of regulatory dendritic cells (DCregs), DCs that show an immunosuppressive behavior, low expression of the stimulatory molecules HLA-DR, and CD86, and high expression of the immunosuppressive molecule programmed death-ligand 1 (PD-L1)." (PMID 30200242, 2018). "Finally, CMT elevated plasma levels of CCL2, which is a monocyte/MDSC chemoattractant promoting tumor progression and metastasis." (PMID 29541413, 2018). "They showed that carlumab in combination with four chemotherapy regimens for the treatment of patients with solid tumors was tolerated well, although no long-term suppression of serum CCL-2 or significant tumor responses was observed." (PMID 28660349, 2018). "TNFα released by tumor cells and cells of TME acts through its receptor TNFR1 and further reinforces TNFα expression and the inflammatory and immune-modulatory network including CXCL12, CCL2, IL-6, VEGF, and macrophage inhibitory factor." (PMID 30154786, 2018).
tumor (continued). "Furthermore, and given that CCL2 expression is a common feature of tumors, our data suggest that enhancing CCR2 expression by NK cells will increase their migration into tumor sites and enhance killing of nascent metastatic deposits." (PMID 30158126, 2018). "In addition, the ascites are rich in soluble agents that support tumor growth and tissue neovascularization, including angiogenin, VEGF, IL-6, CCL2/MCP-1, CXCL1/GRO-1, and CXCL8/IL-8." (PMID 28956065, 2018). "Similarly, CCR2b, the chemokine receptor for CCL2, has been co-expressed on CAR T-cells to exploit the CCR2/CCL2 axis, which facilitates myeloid cell recruitment into the tumor." (PMID 29872437, 2018). "Conversely, the lower Ccl5 to Ccl7 and Ccl5 to Ccl2 expression ratios in F5-T1 support a TME containing less T-lymphocyte chemoattractants and with a greater inflammatory reaction, also attested by the maximal fibrinogen content that characterized this tumor." (PMID 29662647, 2018). "TAMs express chemokine (C-C motif) receptor type 2 (CCR2), a chemokine receptor that interacts with chemokine (C-C motif) ligand 2 (CCL2) and exerts a pro-tumoral role mediating tumor proliferation, angiogenesis, and chemotaxis of immune suppressive cells to the tumor stroma." (PMID 29301364, 2018). "In these models, anti-CCL2 antibody treatment, or genetic deletion of CCR2 inhibits the monocyte migration to the tumor-challenged lung and decreases the number of MAMs, which results in the reduction of metastatic tumor burden." (PMID 30483271, 2018). "The results of the study on the role of CCL2 in various cancers indicated that specificity and sensitivity were 80.00% and 85.00% for CCL2 to differentiate CNS (central nervous system) tumor patients from nontumoral individuals." (PMID 30151375, 2018). "In addition to T cell receptors, nitration of C-C motif chemokine ligand 2 (CCL2) chemokine and STAT1 in splenocytes from tumor-bearing mice have been reported." (PMID 30405034, 2018). "Not only tumor cells, but also the surrounding non-neoplastic stroma express high levels of CCL2, which mediates the recruitment of T lymphocytes, fully differentiated M2 macrophages, and circulating monocytic cell subsets into the tumor environment." (PMID 29751565, 2018). "Furthermore, MLACs recruited MDSCs via the secretion of CCL2/5 and CXCL1/2/5, thereby enhancing the immunosuppressive tumor microenvironment and promoting TAMs-mediated tumor progression." (PMID 29541408, 2018). "Additionally, the oncolytic adenovirus, dl922–947 was shown to modulate tumor microenvironment by decreasing IL-8/CXCL8 and MCP-1/CCL2 expression which resulted in compromised angiogenesis and macrophage infiltration." (PMID 30352606, 2018). "These TIE2-expressing cells are not recruited with CCL2, but via other tumour-derived chemokines as TIE2-ligand angiopoietin 2, CCL3, CCL5 and CCL8." (PMID 30577495, 2018). "Thus, in comparison with WT KLRG1+ NK cells, KLRG1+ NK cells from Ackr2−/− mice increase tumor killing through enhanced CCR2 responsiveness and resulting recruitment in closer proximity to CCL2-expressing tumor deposits." (PMID 30158126, 2018). "Also, recruitment of CD11b/Gr1mid cells depends upon CCL2/CCR2 and its depletion significantly decreases tumor burden." (PMID 29734668, 2018). "In one trial, administration of the anti-CCL2 agent carlumab in combination with four chemotherapy regimens was well tolerated although no significant tumor response was observed." (PMID 29594035, 2018). "The permanent activation of CAFs makes these cells capable of recruiting immune cells from the bloodstream to tumor site through several growth factors, together with other cell types, in particular VEGF, FGF, cytokines, and chemokines, such as CCL2, CXCL12, and CXCL14." (PMID 30249019, 2018). "Though CCL2 treatment did not increase the population of F4/80 or Ly6G cells in the tumor, it did increase the percentage of F4/80 cells that expressed CD206, a marker for M2 macrophages." (PMID 28143493, 2017).
tumor (continued). "Tumor cells produce cytokines responsible for the recruitment and polarization of macrophages to M2 profile such as IL-4, IL-10, IL-13, and TGF-β, as well as chemokines such as CCL2 (MCP-1), CCL3, and CCL14." (PMID 28970834, 2017). "Moreover, TAM derived TGF-β, PGE2, IL-10, and cytokines such as CCL2, CCL17 and CCL18 recruit abundant Tregs to tumor cells." (PMID 29152078, 2017). "However, all tumor cell lines co-cultured with MRC5 fibroblasts secreted high levels IL-6, CCL-2 and IL-8 and low levels of IL-10." (PMID 28750018, 2017). "Exosomes derived from heat-stressed tumor cells (HS-TEX) which contain chemokines, such as CCL2, CCL3, CCL4, CCL5, and CCL20, could chemoattract and activate dendritic cells (DC) and T cells more potently." (PMID 29164149, 2017). "We found that naïve neutrophils isolated from BALB/c mice are indeed able to kill PyMT tumor cells in vitro (p = 0.005), but exogenous CCL2 dids not enhance killing (p = 0.347)." (PMID 28143493, 2017). "The tumor trafficking potential of activated T cells bearing a CAR specific for the tumor antigen GD2 can be enhanced by forced co-expression of the chemokine receptor CCR2b, which directs migration towards CCL2, a chemokine produced by several tumors." (PMID 28331613, 2017). "Tumor-derived chemokines, including CCL2 and CSF1, recruit peripheral monocytes to the tumor site." (PMID 28467800, 2017). "Some other microenvironmental factors such as CSF-1, CCL2, IL6, vascular endothelial growth factor (VEGF-A) and platelet-derived growth factor (PDGF) have also been involved in infiltration of monocytes to the tumour sites." (PMID 29065107, 2017). "We observed CCR2 receptor levels were higher in the FVB neutrophils, indicating that the failure of the FVB neutrophils to respond to exogenous CCL2 with enhanced tumor cell killing was not due to a lack of CCR2 receptor expression." (PMID 28143493, 2017). "Although naïve neutrophils isolated from one mouse genetic background did kill tumor cells derived from another genetic background, exogenous addition of CCL2 did not affect this cytotoxicity." (PMID 28143493, 2017). "The increased macrophage recruitment may be a response to the increased chemokine release by tumor cells such as CXCL-10, CCL-2, CCL3, CCL4, and CCL5." (PMID 28670313, 2017). "In addition, CCL2-mediated activation of SMAD3 and the MAPK pathway are involved in the increased survival of tumor cells and an enhanced metastatic phenotype of these cells." (PMID 28143493, 2017). "Additionally, IFNβ induces expression of CCL2, CCL7 in tumor cells, as well as CCL12 in host cells at the transcription level." (PMID 29170400, 2017). "The Ca2+ binding S100 proteins, released from, for example, necrotic cells of the tumor mass, serve as DAMPs, alarmin molecules to the immune system; one member, the S100B molecule, promoted glioma growth by TAM chemoattraction through CCL2 upregulation and induction of STAT3." (PMID 28197019, 2017). "Treatment with CCL2 blocking antibodies resulted in reduced S100A8/A9 expression and a significantly decreased number of pro-inflammatory monocytes in both spleen and lungs of 4T1.2-tumor bearing mice." (PMID 28744322, 2017). "Furthermore, it has been shown that CCL2 and CCL5 produced by macrophages induce MSC recruitment in tumor sites." (PMID 29069870, 2017). "It has been demonstrated that IVIg significantly hindered secretion of TNF-α, IL-12p40, and CCL2 after M1 macrophages were stimulated with LPS without, nonetheless, affecting their property to inhibit tumor growth." (PMID 28970834, 2017). "We identify endogenous TRAIL-R-induced CCL2 and its activity on host-derived CCR2-expressing cells as crucial for the formation of a tumor-supportive myeloid compartment because TRAIL-R-dependent differences in tumor burden were observed in WT, but not in CCR2-deficient, mice." (PMID 28212753, 2017).
tumor (continued). "In the tumor microenvironment, MSCs also secrete a panel of growth, immunomodulatory, and signaling molecules, such as CCL5, CCL2, TGF-β, VEGF, IL-6, and IL-10, which may play role in angiogenesis." (PMID 29268703, 2017). "We did not observe any biologically significant increase in tumor cell killing in response to CCL2 with 4T1 tumor cells, likely because the naïve neutrophils and TEN alone killed most of the 4T1 tumor cells, leaving little room for enhanced killing." (PMID 28143493, 2017). "This massive recruitment of TAMs is usually facilitated by chemokines like CCL2, CCL5, VEGF, CSF-1, semaphorin 3A (SEMA3A), endothelin, eotaxin and oncostatin M. Once macrophages arrive in these tumour compartments, their migration is halted via hypoxia-dependent mechanisms." (PMID 29065107, 2017). "As we saw with naïve neutrophils, exogenous CCL2 did not enhance tumor cell killing by BALB/c TEN (adj." (PMID 28143493, 2017). "The CCL2 mRNA and protein expression were significantly reduced by l-CDL treatment at the dose of 10 mg/kg or 20 mg/kg group in comparison with tumor group (p < 0.05, p < 0.01), and possessed stronger ability than O&A group and l-THP group in decreasing the expression of mRNA for CCL2 levels." (PMID 28587280, 2017). "Intranasal delivery of CCL2 to BALB/c mice markedly enhanced seeding and outgrowth of 67NR cells in the lung and increased the recruitment of CD4+ T cells and CD8+ central memory T cells into lungs of tumor bearing mice." (PMID 28143493, 2017). "The tumorigenic features of CCL2/CCR2 signaling were described, but CCL2/CCR2 signaling also plays a protective role in antitumor effects, such as through the recruitment of type 1 cytotoxic gammadelta T lymphocytes to the tumor microenvironment." (PMID 28424406, 2017). "In addition, CAF have the capability to recruit immune cells into the tumor region via altering the expression of IL6, CCL2, or NF-kB signals." (PMID 26790618, 2016). "It is thus likely that, in addition to the activation of the STING pathway to activate T cells, NF-κB may also up-regulate the T cell chemokines CCL2 and CCL5 in the tumor cells to attract T cell infiltration into the tumor microenvironment." (PMID 27014915, 2016). "To investigate the kinetics of CCL2 and CCL5 production in the tumor microenvironment, we used the same Colon38 tumor/RT model as before and harvested tumor tissue at different timepoints post-RT, isolated RNA, and quantified the relative amounts of CCL2 and CCL5 transcript by qRT-PCR." (PMID 27852031, 2016). "To determine if RT stimulates tumor cells across different tumor models to produce the chemokines CCL2 and CCL5, we irradiated in vitro cultures of various murine and human tumor cell lines and measured CCL2 and CCL5 transcript levels by qRT-PCR." (PMID 27852031, 2016). "Targeting the CCL2/CCR2 axis is promising as it results in blocking mobilization of monocytes from the bone marrow to the blood, which results in preventing their recruitment to the tumor." (PMID 27191744, 2016). "Although shRNA‐mediated suppression of CCL2 in 786‐O cells did not affect proliferation in vitro, the xenograft tumor growth was reduced compared with that from 786‐O scramble cells in vivo." (PMID 27666332, 2016). "To examine the effect of inhibiting CCL2 activity in the clinical relevant RCC model, we administered CCL2 neutralizing antibodies to primary RCC xenografts, which similarly resulted in significant suppression of tumor growth, angiogenesis, and macrophage infiltration." (PMID 27666332, 2016). "Using a whole genome expression array, we identified 614 genes, which were differentially expressed (P<0.05) in tumor cell from patients with decreased CCL2 plasma levels compared to patients with no change or an increase in CCL2 plasma levels." (PMID 27058904, 2016).